GSTM1 (glutathione S-transferase mu 1)
Diseases named in the same sentence as GSTM1 in open-access papers (continued):
Sharing a sentence is not in itself a finding about the gene and the disease.
anemia (8 papers, 2018 to 2024). A reduction in the number of red blood cells, the amount of hemoglobin, and/or the volume of packed red blood cells. "In contrast, in patients with GSTM1-null genotype the risk of thrombocytopenia and anemia was lower." (PMID 30914949, 2019). "They showed that the homozygous deletion of GSTM1 gene decreased the risk of thrombocytopenia, anemia and neuropathy when compared to such risk in carriers of functional GSTM1 variant." (PMID 29507678, 2018). "Thrombocytopenia, anemia, and neuropathy were less frequent among patients with the GSTM1-null or GSTM3 intron 6 AGG/AGG genotypes." (PMID 30914949, 2019). "Heterozygote CA of p.Gln141Lys (rs2231142) variant increased risk of early anemia nearly 4 times (OR 3.72; 95% CI 1.30–10.66; p = 0.014), together with the presence of both GSTT1 and GSTM1 genes (OR 3.13; 95% CI 1.04–9.40; p = 0.041)." (PMID 29507678, 2018). "In our study homozygous deletion of GSTT1 and GSTM1 genes correlated with nephrotoxicity and anemia analyzed in two settings but, surprisingly, the independent risk factor was not the lack of those genes but their presence." (PMID 29507678, 2018).
Hearing impairment (8 papers, 2007 to 2025). A decreased magnitude of the sensory perception of sound. "In associations of SNVs, it was observed that patients with GSTM1 null plus the XPC c.2815AA genotype had 8.19 greater odds of having moderate/severe hearing impairment (p = 0.02, PA = 99%)." (PMID 36980643, 2023). "Notwithstanding, there is no data in the literature for glutathione S-transferase (GSTT1 and GSTM1) polymorphism be associated to the susceptibility of aminoglycoside-induced hearing loss." (PMID 20658008, 2010). "Functional GSTM1 increased the risk of hearing impairment by 1.8." (PMID 18162130, 2007). "Furthermore, presence of functional GSTM1 nearly doubled the risk of hearing impairment." (PMID 18162130, 2007). "CpG cites in hearing loss candidate genes, KCNQ1, TMEM43, GSTM1, TCF25, and GSR, were found to be highly methylated in presbycusis patients as compared to the controls." (PMID 40428348, 2025). "The findings of study on Brazilian subjects (107 subjects with NIHL, 44 with other causes of hearing loss and 104 controls) suggest effects of GSTT1 and GSTM1 polymorphism on the risk of NIHL." (PMID 31909074, 2019). "A deletion of 3 nucleotides on GSTM3 gene has been shown to have a protective role, whereas having GSTT1 and GSTM1 genes and the A/A genotype at rs1695 in GSTP1 has been associated with hearing loss." (PMID 30112115, 2018). "This study did not detect that the genetic variability of GSTT1 and GSTM1 affect on susceptibility to noise induced hearing loss." (PMID 31909074, 2019). "We showed that 3 of them, rs1695 in GSTP1, the absence of GSTT1, and rs1799793 in XPD/ERCC2 were significantly associated with hearing impairment, whereas rs4880, rs2228001, rs4788863, rs1799735, and presence of GSTM1 were not." (PMID 30112115, 2018). "Thus, this study aimed at assessing the genetic variability of genes GSTM1 and GSTT1 and the ototoxic susceptibility of the aminoglycoside antibiotics in normal-hearing individuals and those with hearing impairment." (PMID 20658008, 2010). "Furthermore, absence of functional GSTM1 protected against hearing impairment (p = 0.025, OR 1.81 [1.08–3.03])." (PMID 18162130, 2007).
melanoma (8 papers, 1995 to 2025). A malignant, usually aggressive tumor composed of atypical, neoplastic melanocytes. "GSTM1 was linked to melanoma, and the protective effect of coffee consumption was reported to be particularly high for subjects with GSTM1 null polymorphisms." (PMID 32210791, 2020). "Some of these include Dead H box helicase 11 (DDX11), Claudin 5 (CLDN5), chemokine CXC motif (CXCL1 ligand 1, melanoma growth), glutathione S-transferase mu 1 (GSTM1), major histocompatibility complex class I K (HLA-K), and thrombospondin 1 (THBS1)." (PMID 36769056, 2023). "In addition, the polymorphism GSTP1 rs1695 and the combined GSTM1 and GSTT1 null polymorphisms have been associated with melanoma susceptibility and with further increase in melanoma risk." (PMID 26064422, 2015). "Furthermore, RAD23 has been shown to be downregulated in glutathione S-transferase M1 (GSTM1)-null melanomas in patients reporting histories of sunburns." (PMID 26052356, 2015). "Considering that high frequency of polymorphisms of CYP2D6 or the polymorphism of VDR, and null for GSTM1 gene in melanoma patients, it is plausible that changes in GSTM1, CYP2D6 and VDR genes may increase the risk for both PD and melanoma." (PMID 26535116, 2015). "In fact, as found in melanoma specimens, A375 cells expressed high levels of GSTP1 and MRP1, whereas very lower levels of GSTM1 and MRP3 were detected." (PMID 15999103, 2005).
Parkinson disease (8 papers, 2012 to 2025). A progressive degenerative disorder of the central nervous system characterized by loss of dopamine producing neurons in the substantia nigra and the presence of Lewy bodies in the substantia nigra and locus coeruleus. "It was also observed that the association between Parkinson disease and pesticide exposure is intensified in the presence of null genotypes for the GSTM1 and GSTT1 genes." (PMID 40243837, 2025). "In the Tunisian population, GSTM1 polymorphism has been found to be significantly associated with the development of tremor as an initial symptom of Parkinson's disease." (PMID 40290119, 2025). "In the Chilean population, the null mutation in GSTM1 has been associated with Parkinson's disease, particularly among younger individuals." (PMID 40290119, 2025). "In addition, reduction of GSTM1 gene expression was associated with Parkinson's disease." (PMID 28596482, 2017). "Gstm1 is expressed in brain, and in the substantia nigra is seen in both dopaminergic neurons and astrocytes and has been implication in control of dopamine metabolism that could have implications in the etiology of Parkinson's disease." (PMID 22291891, 2012).
schizophrenia (8 papers, 2015 to 2025). A major psychotic disorder characterized by abnormalities in the perception or expression of reality. "Schizophrenia patients with the GSTK1 rs1917760*T allele or GSTM1 deletion had a higher risk of being overweight." (PMID 40732231, 2025). "Recent studies have shown an association between GSTM1/T1 deletion polymorphisms and an increased susceptibility to schizophrenia." (PMID 28837637, 2017). "GSTM1 polymorphism was associated with susceptibility to schizophrenia in only East Asian population and GSTT1 and GSTP1 polymorphisms did not related to schizophrenia." (PMID 26295386, 2015). "Thus, the inactive GSTM1 caused by the GSTM1 null genotype can cause not only liver injury but also accumulation of neuro destructive oxidants leading to Schizophrenia." (PMID 26046920, 2015). "In conclusion, our meta-analysis indicated the GSTM1 polymorphism may be the only genetic risk factor for schizophrenia in East Asian population." (PMID 26295386, 2015). "Distribution frequencies of genotype combinations of GSTM1 and GSTT1 in case and control groups and a risk analysis performed with respect to treatment-resistant schizophrenia (TRS)." (PMID 28837637, 2017). "Overall analysis between combination of glutathione S-transferase genes (GSTM1 and GSTT1) and susceptibility of schizophrenia." (PMID 26295386, 2015). "These polymorphisms of GSTM1, GSTT1, and GSTP1 have been investigated with various diseases including schizophrenia, hypertension, and capacity for oxidation and detoxification." (PMID 26295386, 2015). "Overall analysis between polymorphisms of glutathione S-transferase genes (GSTM1, GSTT1, and GSTP1) and susceptibility of schizophrenia." (PMID 26295386, 2015). "Therefore, we performed a meta-analysis to explore the association between the GSTM1, GSTT1, and GSTP1 polymorphisms and the risk of schizophrenia." (PMID 26295386, 2015). "Therefore, we performed a meta-analysis on all eligible case-control studies to clarify the association between the GSTM1, GSTT1, and GSTP1 polymorphisms and risk of schizophrenia." (PMID 26295386, 2015). "Our meta-analysis results revealed that GSTM1, GSTT1, and GSTP1 polymorphisms were not related to risk of schizophrenia (p > 0.05 in each model)." (PMID 26295386, 2015).
chronic obstructive pulmonary disease (7 papers, 2015 to 2025). A chronic and progressive lung disorder characterized by the loss of elasticity of the bronchial tree and the air sacs, destruction of the air sacs wall, thickening of the bronchial wall, and mucous accumulation in the bronchial tree. "In chronic obstructive pulmonary disease, GSTM1/GSTT1 variants are associated with an elevated risk, particularly in cases of emphysema." (PMID 40290119, 2025). "Ding et al127 have also found an alliance of null GSTM1 and GSTT1 genotypes with the increased risk of chronic obstructive pulmonary disease." (PMID 40290119, 2025).
Cirrhosis (7 papers, 2016 to 2025). A chronic disorder of the liver in which liver tissue becomes scarred and is partially replaced by regenerative nodules and fibrotic tissue resulting in loss of liver function. "The GSTM1 (glutathione S-transferase mu) locus is also a polymorphic locus associated with cancers, metabolism, and hepatic cirrhosis." (PMID 37403156, 2023). "Subgroup analysis of cirrhosis type revealed that GSTM1 null was a prominent risk factor for alcoholic HC (OR = 1.416, 95% CI 1.112–1.804, p = 0.005)." (PMID 29921322, 2018). "A lot of studies were performed to explore the association of GSTM1 gene polymorphism with cirrhosis risk." (PMID 29921322, 2018). "As to the control source subgroup analysis, GSTM1 null is a risk factor of hepatic cirrhosis in hospital-based studies (OR = 1.426, 95% CI 1.092–1.863, p = 0.009)." (PMID 29921322, 2018). "The analysis using the multiple PCR genotyping method showed a significant association between GSTM1 null genotype and hepatic cirrhosis occurrence (OR = 1.559, 95% CI 1.171–2.076, p = 0.002)." (PMID 29921322, 2018). "Thus, the fixed-effect model was used to assess the strength of the relationship between GSTM1 null genotype and risk of hepatic cirrhosis." (PMID 29921322, 2018). "The Kotb disease variant proved to be due to congenital aflatoxicosis in GSTM1 null neonates, resulting in massive inflammation induced by neutrophils, adhesions, and obliteration followed by fibrosis of extrahepatic biliary radicals, accelerated cirrhosis and portal hypertension." (PMID 36181129, 2022). "Previous reports have associated GSTM1 deficiency with various fibrotic diseases, such as oral mucosal fibrosis, cystic fibrosis, and cirrhosis, suggesting a broader role of GSTM1 in regulating fibrosis." (PMID 40448227, 2025). "Carriage of GSTM1 null and rs2066701CC genotype of ADH1B were found to be associated with increased risk of progression of ALC to decompensated cirrhosis." (PMID 26937962, 2016). "According to the analysis results of this study, GSTM1 null is associated with the increased risk of non-viral hepatic cirrhosis." (PMID 29921322, 2018). "It is reported that glutathione S-transferase mu (GSTM1) polymorphism is associated with non-viral hepatic cirrhosis (HC)." (PMID 29921322, 2018). "In this paper, a meta-analysis was performed to investigate the association between GSTM1 gene polymorphism and non-viral cirrhosis susceptibility." (PMID 29921322, 2018). "Based on the results of this analysis, it was concluded that GSTM1 null genotype could increase the susceptibility of non-viral hepatic cirrhosis." (PMID 29921322, 2018). "First, this paper is focused on GSTM1 polymorphism and the risk of non-viral hepatic cirrhosis." (PMID 29921322, 2018). "Compared with control groups, the pooled OR of GSTM1 null in non-viral hepatic cirrhosis is 1.337 (95% CI 1.062–1.684, p = 0.013), which indicates that null GSTM1 is associated with an increased risk of non-viral hepatic cirrhosis." (PMID 29921322, 2018).
Infertility (7 papers, 2015 to 2025). "The presence of GSTT1 and GSTM1 null genotypes is associated with an increased vulnerability to infertility." (PMID 40283113, 2025). "In conclusion, our results suggest that the presence of GSTM1-null genotype is associated with almost a 3-fold higher risk for infertility in women." (PMID 38068321, 2023). "Even though many studies focused on the effects of GSTM polymorphisms on fertility issues, there is only one study from Northern Iran reporting the effect of GSTM1 polymorphism in infertility and pregnancy rate." (PMID 38068321, 2023). "The present study was designed to investigate the possible association between the presence of GSTM1-null genotype and infertility in women undergoing IVF treatment." (PMID 38068321, 2023). "More importantly, a similar relative risk for male factor infertility was observed in patients with the GSTM1-null genotype." (PMID 37959238, 2023). "Infertile individuals with the GSTM1-null genotype are more susceptible to oxidative stress than GSTM1-positive infertile males." (PMID 37959238, 2023). "We analysed the two-way combination of GSTM1 and CYP19A1 genotypes and found that when GSTM1 is present, there is a significant association with infertility risk (OR 3.216; 95% CI (1.715–6.031; p < 0.001)." (PMID 37107315, 2023). "The aim of the present study is to investigate the effect of GSTM1 polymorphism and static redox potential (sORP) to the basic seminal parameters of fertile and infertile men." (PMID 37959238, 2023). "We found that homozygosity or heterozygosity for the C allele was significantly associated with an increased risk of infertility in the study population, and we again demonstrated the impact of GSTM1 and GSTT1 polymorphisms on female infertility." (PMID 37107315, 2023). "For Iranian population, an increased risk of infertility in the patients with null genotype of GSTM1 and GSTT1 has been reported." (PMID 29766145, 2018). "A subject carrying the variants CYP1A1 Val/Val or CYP1A1 Ile/Val in association with GSTM-null genotype has a 6.90-fold higher risk for infertility than a subject carrying CYP1A1 Ile/Ile in association with a GSTM1 wild-type genotype." (PMID 26618172, 2015). "The GSTM1-null genotype is only associated with all causes of infertility when the GSTT1 is null." (PMID 40283113, 2025). "The aim of the present study is to investigate whether the presence of GSTM1-null polymorphism is associated with an increased risk for infertility." (PMID 38068321, 2023). "Thus, an increased risk of the GSTM1 polymorphism for developing male factor infertility is supported." (PMID 37959238, 2023). "In addition, GSTM1 polymorphism plays an important role in infertility, for which reason these patients require treatment adjustment." (PMID 36013572, 2022). "Regarding GSTs polymorphisms, our group previously confirmed a significantly increased risk of infertility associated with GSTT1 and GSTM1 null genotypes, alone or in association." (PMID 37107315, 2023). "Another study also demonstrated lower sperm concentration and motility in infertile men carrying the GSTM1-null genotype compared to fertile ones with the GSTM1-positive genotype." (PMID 37959238, 2023). "The frequency of the GSTM1-null genotype was higher in infertile male individuals (31/51; 60.78%) than in the controls (16/39; 41.03%), with an OR of 2.228, but it was not statistically significant." (PMID 37959238, 2023). "From the total of samples investigated, in the infertile group (n = 125), the GSTM1 gene (wildtype) was detected in 76/125 and the GSTM1-null genotype (deletion) was detected in 49/125 samples." (PMID 38068321, 2023). "Specifically, it focused on the possible impact of the GSTM1 polymorphism on different IVF parameters, reproductive hormonal levels, and pregnancy outcome in infertile women, who underwent IVF treatment." (PMID 38068321, 2023).
Infertility (continued). "Ultimately, the importance of our results lies in the confirmation that the GSTM1-null genotype and sORP values affect both fertile and infertile males in different ways." (PMID 37959238, 2023). "In a Turkish population, increased oxidative damage of sperm was higher in patients with the GSTM1-null genotype than in controls, and similar results have also been reported in Egyptian, Iranian, and Brazilian infertile patients." (PMID 26618172, 2015). "As a surrogate marker of infertility, GSTM1-null genotype presents a promising result through the reported correlation and further data should validate its importance in the investigation of female factor infertility." (PMID 38068321, 2023). "Similarly, the frequency of the GSTM1-null genotype was significantly higher in infertile individuals than in fertile ones." (PMID 37959238, 2023). "This work highlights the great influence of CYP19A1 codon 39 Trp/Arg (T/C) polymorphism (rs2236722) and GSTM1 and GSTT1 polymorphisms in female fertility and brings to discussion the value of assessing low penetrance polymorphisms to prevent infertility in the general population of women." (PMID 37107315, 2023). "This study confirmed that GSTM1-null genotype was present in 39% of the infertile women, hence its presence may be related with reproductive pathological conditions and infertility." (PMID 38068321, 2023). "In addition, GSTP1 wild-type genotype in combination with GSTM1 null or GSTT1 null genotype increased the probability for infertility." (PMID 29766145, 2018). "A previous study has shown a significant synergism between GSTM1 and CYP1A1 genotypes and infertility among human subjects." (PMID 26618172, 2015). "In conclusion, our study showed that the GSTM1-null genotype does not significantly affect the semen parameters of the infertile group." (PMID 37959238, 2023). "This analysis aimed to investigate whether the absence of GSTM1 gene affects conventional semen parameters, such as morphology and motility, in fertile and infertile men." (PMID 37959238, 2023).
liver cancer (7 papers, 2002 to 2025). An epithelial or non-epithelial malignant neoplasm that arises from the liver. "Genetic differences in AFB1 biotransformation pathways (such as the GSTM1 genotype) further complicate the quantitative extrapolation of laboratory animal data to human liver cancer risk." (PMID 39852983, 2025). "GSTM1 also promoted cancer chemotherapy drugs or apoptosis escaping pathways to induce chemoresistance in liver cancer." (PMID 35965498, 2022).
nasopharyngeal carcinoma (7 papers, 2009 to 2024). A carcinoma arising from the nasopharyngeal epithelium. "A number of studies have conducted on the association of GSTM1 and GSTT1 polymorphism with susceptibility to nasopharyngeal carcinoma (NPC)." (PMID 19338664, 2009). "Subgroup results also showed that high risk of lung and nasopharyngeal cancer could be found in both smokers and nonsmokers, but GSTM1-null could lead to increased cancer risks of the stomach, the cervical and the bladder even nonsmoking." (PMID 38579033, 2024).
thalassemia (7 papers, 2016 to 2024). An inherited blood disorder characterized by a decreased synthesis of one of the polypeptide chains that form hemoglobin. "An increased risk of cardiac complications related to the GSTM1 haplotype, the ApoE ε4 allele, and some HLA haplotypes has been reported in patients with thalassemia major." (PMID 39062234, 2024). "Importantly, GSTM1 deletion has been associated with increased cardiac iron in thalassemia major and increased disease severity in patients with SCA." (PMID 31694285, 2019). "Glutathione-S transferase gene deletions (GSTM1 and GSTT 1) have also been associated with increased cardiac iron deposition in patents with thalassemia who are receiving chronic transfusion therapy." (PMID 31694285, 2019).